MIR934 (microRNA 934)
Synonyms: hsa-mir-934; MIRN934; mir-934
Gene: MicroRNA gene on chromosome X (136,550,878 to 136,550,960, forward strand). Ensembl gene ENSG00000216060.
Gene Ontology:
Biological process: miRNA-mediated post-transcriptional gene silencing
Cellular component: RISC complex
Homologues: Orthologues: chimpanzee ptr-mir-934 (100% identical), macaque mml-mir-934 (94% identical).